CCL2 (C-C motif chemokine ligand 2)
Diseases named in the same sentence as CCL2 in open-access papers (continued):
Sharing a sentence is not in itself a finding about the gene and the disease.
tumor (continued). "These MAMs secrete additional CCL2 to further augment TAM recruitment to metastatic sites, and CCL3 which instigates tumor seeding at distant sites." (PMID 33381449, 2020). "Analyses from adjacent normal and GC samples confirmed that immune-related status was passive in the tumor microenvironment compared to normal tissues, as reflected by scarce expression of chemokines CXCL9, CXCL10, and CCL2, leading to IFN-γ restriction." (PMID 31903134, 2020). "Characterized by their hallmark cytokines, IL-10 and TGF-β, which can effectively suppress tumor-specific T cell activation, Tregs are attracted to the local tumor environment by soluble mediators, such as CCL22 or CCL2 produced by glioblastoma cells." (PMID 32117316, 2020). "By contrast, CCL2 induced the Th1 and CD8+ T cells and natural killer (NK) cells recruitment into the tumor microenvironment (TME), determining cancer cell death, thus contributing to prolonged patient survival." (PMID 31991677, 2020). "IL-17 induces the secretion of CCL2, CXCL1, CXCL5, CXCL6, and CXCL8 from several types of cells that infiltrate the tumor, and subsequently, it recruits myeloid-derived suppressor cells, including tumor-associated macrophages." (PMID 32756356, 2020). "The most important function of CCL2 is the CCR2-mediated recruitment of TAM and MDSC into the tumor niche." (PMID 33182504, 2020). "CCL2 is expressed in tumors and affects endothelial permeability and metastasis through interacting with CCR2 expressed on tumor endothelial cells." (PMID 31690961, 2020). "Thus, to examine whether there are common tumor-promoting factors between parent and resistant cells that enhance neutrophil survival, we tested the expression of pro-inflammatory factors such as IL-1β, CCL2, CCL3, CCL4, IL23, and iNOS in neutrophils." (PMID 33049964, 2020). "Among these chemokines and cytokines, we selected CXCL8, CCL2, CXCL10, and CCL20 for further study because of their critical role in cell infiltration into the tumor microenvironment." (PMID 32971847, 2020). "Anti-CCL2 treatment inhibits the expression of arginase 1 and iNOS, thereby reducing G-MDSC and M-MDSC in and around the tumor." (PMID 32000802, 2020). "CCL2 produced by murine GBM cells recruits CCR4+Tregs and CCR2+Ly-6C+ mMDSCs while MIF produced by tumor stem cells activates MDSCs, resulting in an immunosuppressive tumor microenvironment." (PMID 32707672, 2020). "On the other hand, RT can induce the recruitment of macrophages into the tumor tissue by stimulation of CCL2, CSF1 production and promote the tumor progression." (PMID 33062602, 2020). "MCP-1/CCL-2 secreted by GBMs is capable of trafficking MDSCs into the tumor microenvironment and felicitated tumor growth via MDSCs." (PMID 33204365, 2020). "Altogether, these findings provide a plausible mechanism for CCL2 in the recruitment of CCR2-expressing myeloid cells subsets to the tumor, thus promoting macrophage tumor infiltration and macrophage-mediated development of lymphatic metastasis." (PMID 31811337, 2020). "In particular, mediators like CSF-1, CCL2 and vascular endothelial growth factor (VEGF) promote TAM accumulation in the tumor microenvironment." (PMID 32708142, 2020). "In a mouse tumor model from a breast metastasis cell line (MDA-MB-231), stimulation of CCL2 expression by M2 macrophages was recently shown." (PMID 32429318, 2020). "While most adipokines promote bone metastasis, there are a few that suppress bone metastasis, namely CCL2/MCP-1, which inhibits bone metastasis by suppressing ICAM-1 expression and anchorage-independent tumor cell growth and cell migration." (PMID 32674405, 2020). "M1 macrophages can destroy tumor cells by producing inflammatory cytokines such as tumor necrosis factor (TNF)-α, IL-12, CXCL10 (IP10), CCL2 and nitric oxide (NO)." (PMID 32196489, 2020). "Chemokine C-C motif ligand 2 (CCL2), in addition to the promotion of angiogenesis, also enhances tumor metastasis." (PMID 32855630, 2020).
tumor (continued). "Activated MDSCs flow through the blood and spleen and are eventually recruited to the tumor site by C–X–C motif chemokine ligand 1 (CXCL1), C–C motif chemokine ligand 2 (CCL2), and other chemokines." (PMID 32942545, 2020). "We therefore used mouse and human-specific primers to assess the expression of CCL2 in tumor tissues and found that the ACC-Meso-1 tumor expressed much higher levels of CCL2 at the baseline (approximately 16,000-fold higher than MSTO211H)." (PMID 33233664, 2020). "Three fractions of RT increased the concentrations of seven inflammatory mediators in tumor tissues: GM-CSF, IL-17, CXCL1, CXCL2, CCL2, CCL5 and TNFα." (PMID 31752313, 2019). "Persistent tumor release of growth factors and cytokines (such as G-CSF, GM-CSF, and VEGF), promote MDSC production in the BM, whereas tumor release of chemokines (i.e., CCL2, CXCL12) recruits them within the tumor microenvironment (TME)." (PMID 31281314, 2019). "An array of tumor-derived chemoattractants such as CSF1, CSF2, CCL2, VEGFA, and SEMA3A contribute to the recruitment of monocytic precursors, resulting in TAMs accumulation." (PMID 31406165, 2019). "During tumor development, cancer cells secrete chemokines such as CCL2, CCL5, CXCL12, and colony stimulating factor 1 (CSF1) to recruit immune cells towards the tumor site." (PMID 31766635, 2019). "Among them, CCL2 was continuously overexpressed, while the expression of other chemokines decreased significantly at the later stage both in residual CT26 and MC38 tumor." (PMID 31780645, 2019). "Factors such as CCL-2, CCL-5, CCL-17, CCL-22, CXCL-12, M-CSF, VEGF, and TGF-β synthesized by the tumor stroma aid in the recruitment of monocytes and subsets of T cells." (PMID 31134198, 2019). "To understand if NFATc3 is a critical factor for cytokines and chemokines known to be involved in tumour growth, we evaluated the impact of nuclear NFATc3 on TNF-α, CXCR-3, GM-CSF, IL-2 and CCL-2 mRNA expression." (PMID 31249342, 2019). "It was shown that CCL2 is a downstream target of HOTAIR and is involved in the recruitment of myeloid-derived suppressor cells (MDSCs) and macrophages to the tumor microenvironment." (PMID 31056726, 2019). "Of these, priming of toll-like receptors TLR3 and TLR4 seems to significantly affect MSC interactions with tumor cells and we propose this to be the key role in MSC and GB cross-talk via CCL2/MCP1 cytokines." (PMID 31167364, 2019). "Ninety percent of PitNETs secreted IL-8, CCL2 and CCL3, while CXCL1 was secreted by 50% of the tumours." (PMID 31703742, 2019). "Tumor-resident MSCs release a large amount of various chemokines, including CCL-2, CCL-7 and CCL-12, thereby enhancing the recruitment of monocytes expressing CCR2 into tumor sites and increasing the number of macrophages and growth of tumors." (PMID 31336889, 2019). "During early tumor lesions, TAMs are recruited in a HCC environment mainly via CSF-1, CCL2, VEGF, and TGF-β, and in turn release additional cytokines, chemokines, and growth factors that promote HCC progression." (PMID 31611871, 2019). "Cytokines like CCL2, and SDF-1 are expressed in tumor stroma, and strong evidence indicates that these cytokines are associated with TAM accumulation." (PMID 30894509, 2019). "FAP+ CAFs modulate the tumor microenvironment through secretions such as C-C motif chemokine ligand 1, 2 and 5 (CCL1, CCL2, CCL5) and CXCL12 in HCC." (PMID 31540435, 2019). "Reverse transcription polymerase chain reaction (RT-PCR) revealed that Gal-1 knockdown abrogated CCL2 and VEGF-A mRNA expression in the tumor, resulting in decreased recruitment of MDSCs to the TME and decreased angiogenesis, respectively." (PMID 31396227, 2019). "There is considerable interest in developing therapies that target CCL2/CCR2 and tumor-resident myeloid cells." (PMID 31823764, 2019).
tumor (continued). "CCL2 and CXCL10, showed higher relative mRNA expression levels in tumors than in normal lamina propria of tumor bearing Apc1638N/+ mice correlating with the recruitment of myeloid cells and T lymphocytes into the tumors." (PMID 31681563, 2019). "In mice harboring mammary tumors, we found that the depletion of TAM resulted in more inflammatory chemokines, such as CCL2 and CXCL10, which are likely to enhance the entry of T cells into the tumor and their intratumoral migration." (PMID 31354719, 2019). "Cytokines and chemokines derived from tumor cells and cancer-associated fibroblasts (CAFs), such as CSF-1, CXCL12/SDF1, CCL2/MCP-1, CCL5/RANTES, and VEGF, recruit mononuclear cells into the tumor microenvironment and activate them to become TAMs or MDSCs." (PMID 31554173, 2019). "The decrease of the monocyte-attracting chemokine MCP-1/CCL2 reduced monocyte chemotaxis in vitro and tumor macrophage density in vivo." (PMID 31636245, 2019). "Both CCL2 and CCL4 suppress infiltration of macrophages and immune cells to the tumor site and are related to an advanced stage and poor prognosis." (PMID 31398937, 2019). "CCL2, CCL5 and IDO play key roles in promoting tumor growth and progression partially by inhibiting the immune response against cancer through Tregs." (PMID 30808421, 2019). "For instance, CCL2, VEGF, M-CSF etc. secreted by the tumor stroma, attract and recruit the circulating monocytes into the microenvironment." (PMID 30925924, 2019). "When the tumor purity or age option was adjusted, the expression scatterplots between CTRP1 and CCL2 still had statistical significance (purity: partial." (PMID 31183364, 2019). "MDSCs are recruited into the tumor site by the malignant cells by increasing the level of various soluble factors including IL-6, GM-CSF, TGFβ, VEGF and chemokines such as CCL2 and CCL5, in the tumor microenvironment." (PMID 31231358, 2019). "CXCL12 and CCL2 can promote angiogenesis and inhibit apoptosis of endothelial cells by directly binding their receptor (CXCR4 and CCR2, respectively) expressed on tumor vessels or indirectly promoting the recruitment of leukocytes." (PMID 30894861, 2019). "The number of CCL2+ or CCL17+ TANs is related to tumor size, microvascular infiltration, tumor embedding, tumor differentiation and staging." (PMID 31464625, 2019). "For instance, previous studies had shown strong correlation between CCL2, which is downregulated in BC tissue, expression and TAM infiltration and tumor progression." (PMID 31620367, 2019). "One of the most studied TME factors, chemokine (C-C motif) ligand 2 (CCL2), also known as monocyte chemoattractant protein 1 (MCP-1), is expressed by tumor cells, and its expression correlates with poor prognosis in most human tumors." (PMID 31861801, 2019). "CD4+ helper T lymphocytes react to CAF secretion of CCL2, CCL5, and CCL17 along with polarizing cytokines IL-1, IL-6, IL-13, and IL-26 by switching from an anti-tumor TH1 response to a pro-tumor TH2 and TH17 response." (PMID 31058816, 2019). "On the other hand, CCL2 expression in human HCC directly correlates with the infiltration of effectors cells, such as CD4+ Th1, CD8+ and NK cells, which contributes to tumor eradication." (PMID 31377844, 2019). "Both CCL2 and CXCL16 are expressed in tumor tissues, such as lung carcinoma, hepatocellular carcinoma, colorectal cancer, and brain and ovarian cancers, hence it is possible that they play a role in the migration of MSC into tumors." (PMID 31555593, 2019). "The tumor-stroma-inflammation network was found in our study to strongly induce the expression of the pro-metastatic chemokines CXCL8, CCL2 and CCL5." (PMID 31031757, 2019). "Recent studies demonstrated that the CCL2/CCR2 axis is responsible for the M2 polarization of TAMs, thereby shaping a tumor-supportive environment." (PMID 31024838, 2019).
tumor (continued). "Tumor-derived CCL2 is released into the TME and recruits macrophages to tumor cells, which contribute to tumor cells proliferation, angiogenesis, and immune response evasion." (PMID 31448238, 2019). "Therapies are being developed that target CCL2/CCR2 and tumor resident myeloid cells, and clinical trials are being pursued that use these therapies as part of the treatment regimen." (PMID 31823764, 2019). "And they can modify TME that subsequently leads to tumour cell proliferation by producing proangiogenic factors (CXC12, VEGF, FGF, IL8/CXCL8, and PDGF-C), CCL-2, IL-6, FAP, IL-4, hyaluronan, IL-8, CXCL9, CXCL10, CXCL12, and Fsp1." (PMID 30944831, 2019). "Among the others, CCL2, CCL3, and CCL5 contribute to tumor vascularization and metastasis and also stimulate MMP9 secretion by monocytes, which strongly favors tumor cell extravasation." (PMID 31484464, 2019). "We also investigated the chemotactic cytokine C-C motif chemokine ligand 2 (CCL2), referred to as monocyte chemoattractant protein 1 (MCP1), which is important for the recruitment of monocytes/macrophages during tumor metastasis." (PMID 30705401, 2019). "Classically, it is dependent on bloodstream-derived monocyte infiltration mediated by CCL2, CCL7, CXCL12, VEGF, and other cytokines produced in the tumor microenvironment by stromal and tumor cells." (PMID 31275860, 2019). "M2 TAMs can produce growth factors and cytokines such as CCL2, CXCL12, CXCR4, TGFβ, VEGF, PDGF, COX-2 and metalloproteinases that determine immunesuppression and stimulate local tumor growth as well as the metastatic process." (PMID 31500586, 2019). "It was reported that both small molecular inhibitors and antibodies targeting either CCL2/CCR2 or CSF-1/CSF-1R signaling axis obviously inhibited the mobilization of monocytes and macrophages accumulation in tumor sites." (PMID 31300030, 2019). "Further, systemic administration of CCL2 neutralizing antibody by itself or in combination with temozolomide (TMZ) reduces accumulation of MDSCs and enhances the survival of tumor bearing mice." (PMID 30619286, 2018). "YAP activates expression of cytokines and chemokines such as C-C motif chemokine ligand 2 (CCL2) and colony stimulating factor 1 (CSF1), thus recruiting macrophages to tumor-initiating cells to protect them from immunosurveillance." (PMID 30453531, 2018). "In the TME, the presence of CAFs and their secretion of CCL2, CCL5, and CCL17 as well as the polarizing cytokines IL-1, IL-6, IL-13, and IL-26 can favor a tumor promoting TH2 and TH17 immune response, as the expense of tumor protective TH1 response." (PMID 29545811, 2018). "Our results have identified a previously unappreciated driver of LUSC metastasis characterized by CCL2-mediated recruitment of IMs and FXIIIA-mediated fibrin cross-linking in the TME, which provides a scaffold for tumor cell invasion." (PMID 29777108, 2018). "Secondly, ZA has been reported to decrease CCL2 expression in early-stage breast cancer model, preventing TAM recruitment and reducing tumour growth." (PMID 30577495, 2018). "Tumor cell overexpression of S1P3 mimics this pathway, enhancing IL-6 and CCL-2 production and elevating BTB permeability." (PMID 30006619, 2018). "The sensitivity of the tested parameters in the total cancer group was higher for CCL2 (64.95%) than for CCR2 (61.86%) and higher than for routinely used tumor marker CA 15-3 (59.79%)." (PMID 30151375, 2018). "In turn, growth promoting factors including IL6, CCL2, VEGF, and CXCL2 are released from the osteoblasts, which promote tumor cell growth, again initiating an additional cycle." (PMID 29642534, 2018). "Reasonable hypotheses are that the CCL2-elicited IMs may play similar roles to TAMs by providing both a pro-tumor, pro-metastatic microenvironment through the secretion of growth factors as well as by being highly immunosuppressive, thus preventing an anti-tumor immune response." (PMID 29777108, 2018).
tumor (continued). "For example, we have previously shown that the local tumour microenvironment of mCRC patients contains high levels of the chemokines CXCL1, CXCL5, and CCL2 which have proangiogenic properties." (PMID 29535825, 2018). "Primarily, they contribute to the homing of cancer cells and fulfill this role upon their mobilization from the blood by tumor-derived chemoattractants (e.g., CCL2/MCP-1, IL-6, MIF, and CSF-1) and differentiation into TAMs." (PMID 28956065, 2018). "Bone marrow-derived monocytes (F4/80low) are recruited to the tumour via secretion of CSF1 and monocyte chemoattractant protein 1 (MCP1 or CCL2)." (PMID 30577495, 2018). "Focusing on CXCL12, CCL2, and CCL22, all three chemokines aid tumor development and progression by recruiting immune suppressive cell subsets." (PMID 30126117, 2018). "The interaction between CCL2 and its primary receptor CCR2 is crucial for recruiting large numbers of monocytes to the tumor tissue." (PMID 30059519, 2018). "Consistent with our mouse tumor model with reduced IGF-1R signaling, low IGF-1R is inversely correlated with IL-6, CCL2, and MMP9 expression in human tumors." (PMID 30458886, 2018). "CC chemokines, especially MCP1 (CCL2) and CCL5, are major attractants of monocyte and macrophage precursors to the tumor microenvironment." (PMID 29573228, 2018). "CCL2 in turn facilitated the recruitment of M-MDSC and macrophages, promoting metastatic tumor growth." (PMID 29915603, 2018). "Chemokine axes, such as fractalkine (CX3CL1)/CX3CR1, C-X-C motif chemokine ligand 12 (CXCL12)/C-X-C chemokine receptor type 4 and 7(CXCR4/CXCR7), CCL2/CCR2, and CCL5/CCR5, are clearly involved in tumor progression." (PMID 30123112, 2018). "Chemokines (CCL2, CCR2, CCL5, etc.)produced by different tumors can actively recruit MDSCs to primary and metastatic tumor sites to inhibit immune cell function within the TME." (PMID 29735917, 2018). "For example, CCL2 (MCP‐1) and CCL5 (RANTES) are major attractants of monocyte precursor cells in tumours and, when accumulated, these cells play an important part in tumour non‐responsiveness by suppressing antigen‐specific T cell responses." (PMID 30117676, 2018). "It has been proved that blocking of the CCL-2/CCR-2 axis decreased macrophage infiltration and reduced tumor growth." (PMID 28660349, 2018). "Similar to MDSCs, TAMs and TANs are recruited to tumor sites by tumor-derived chemokines and growth factors, including CCL2/MCP-1, CXCL1/Gro-a, CCL7/MCP-3, CCL5/RANTES, CXCL8/IL-8, VEGF, PDGF, and M-CSF/CSF-1." (PMID 29735917, 2018). "Macrophages are attracted to hypoxic regions of tumor by hypoxia-induced chemoattractants secrete by tumor cells, i.e.: VEGF, endothelin, CCL2." (PMID 29320562, 2018). "Diverse chemokines, i.e., CCL2 (MCP-1), CCL5 (RANTES), CCL7 (MCP-3), CXCL8 (IL-8), and CXCL12 (SDF1), released by tumor cells induce migration, differentiation, and survival of tumor-infiltrating myeloid cells." (PMID 29686671, 2018). "IL-1β induces CCL2 expression in TAM and tumor cells as well, regulating myeloid cell recruitment into tumor tissue." (PMID 30042333, 2018). "The area under ROC curve was the highest for the combination of CCL2 and CCR2 with commonly accepted tumor marker, which indicates a possible clinical significance of plasma CCL2 and CCR2 measurements in the diagnosis of BC." (PMID 30151375, 2018). "In tumor models, neutrophils can be converted from anti-tumor phenotype (N1: release ROS and TNF-α) to pro-tumor phenotype (N2: increased Arginase, CCL2, and CCL5) by the TGF-β stimulation." (PMID 29776443, 2018). "In particular, the chemokines CCL2, CCL3, IL-8/CXCL8, and CXCL12 are consistently involved in promoting osteoclastogenesis and tumor growth." (PMID 29930538, 2018). "CCL2 (MCP-1) is proinflammatory chemokine; therefore, studies have demonstrated its overexpression or increased serum levels and resultant promotion of tumor growth in breast." (PMID 30151375, 2018).